STAT3 (signal transducer and activator of transcription 3)
Diseases named in the same sentence as STAT3 in open-access papers (continued):
Sharing a sentence is not in itself a finding about the gene and the disease.
osteosarcoma (continued). "However, in the case of osteosarcoma, FNDC5/Ir inhibited STAT3 phosphorylation in the STAT3/SNAIL signaling pathway, which is also associated with the EMT process." (PMID 37239973, 2023). "Likewise, the combination of ferroptosis agonists (erastin and RSL3) and STAT3 (signal transducer and activator of transcription 3) inhibitors synergistically impaired the cisplatin resistance in osteosarcoma MG63 and Saos-2 cells." (PMID 36819098, 2023). "In addition, BMSC-derived exosomes carrying proteins, such as LCP1, stimulated osteosarcoma metastasis via the LCP1-induced activation of the JAK2/STAT3 signaling pathway." (PMID 37377390, 2023). "We identified that TSN was a potential inhibitor of eEF2, although it was reported that TSN could bind with STAT3 in osteosarcoma tumor." (PMID 37088855, 2023). "In addition, JAK2 and STAT3 expression were reduced by silencing of FANCD2, and STAT3 activator (colivelin) distinctly reversed tumor suppressor effects of FANCD2 silencing on osteosarcoma development." (PMID 36814203, 2023). "They referred to a previous study in which STAT3 was inhibited in osteosarcoma cell lines in MSC-preconditioned medium by short interfering RNA or AG490 (Janus kinase/STAT inhibitor), resulting in a decrease in cell invasion, proliferation, and migration rates." (PMID 36831259, 2023). "It was previously reported that Siglec-15 knockdown could reduce STAT3 signalling thus inhibiting cellular proliferation and inducing apoptosis in osteosarcomas." (PMID 37869015, 2023). "Interestingly, a later study identified ADSCs to interact with osteosarcoma cells via the STAT3 pathway." (PMID 36831259, 2023). "We thus sought to determine if a STAT3 inhibitor could selectively target osteosarcoma lung metastasis." (PMID 37938582, 2023). "Furthermore, IL-22 accelerates the proliferation and invasion of osteosarcoma cells by activating STAT3." (PMID 35669104, 2022). "Overall, because of its STAT3 signaling inhibitory action, pectolinarigenin may be beneficial to treat osteosarcoma." (PMID 35327559, 2022). "Bruceine D decreases CSCs and tumor growth by targeting STAT3 signaling in osteosarcoma." (PMID 35333774, 2022). "Regarding the management of osteosarcoma, preclinical studies have shown that apatinib promotes apoptosis and autophagy through VEGFR2/STAT3/BCL-2 signaling pathways in osteosarcoma cells, as well as attenuates invasion and migration through RhoA/ROCK/LIMK2 pathways." (PMID 36387068, 2022). "miR-125: acts as a tumor suppressor in cancer; miR-125b is frequently down-regulated in osteosarcoma and its ectopic restoration suppresses cell proliferation and migration, indicating that signal transducer and activator of transcription 3 (STAT3) is its direct and functional target." (PMID 35216464, 2022). "Specifically, the STAT3 pathway is a crucial regulator involved in osteosarcoma tumorigenesis." (PMID 36151091, 2022). "In osteosarcoma, STAT3 induces resistance to doxorubicin and cisplatin in Saos-2 and U2-OS cells." (PMID 36620587, 2022). "FNDC5 was shown to inhibit EMT through the modulation of STAT3/Snail pathway in osteosarcoma." (PMID 36386179, 2022). "Moreover, in osteosarcoma cells, overactivation of STAT3/NRF2 signaling can lead to cisplatin resistance by increasing glutathione peroxidase 4 (GPX4) activity, thereby suppressing ferroptosis." (PMID 36557902, 2022). "The study identified that ferroptosis sensitization could be induced by dampening STAT3/Nrf2/GPx4 signaling to enhance the sensitivity of osteosarcoma cells to cisplatin." (PMID 35402247, 2022). "Furthermore, when osteosarcoma mice were injected with MSCs and Saos-2 cells, the inhibition of STAT3 improved survival by suppressing tumour growth and increasing their susceptibility to doxorubicin." (PMID 35954425, 2022).
osteosarcoma (continued). "More importantly, we demonstrated that overexpression of PRMT1 rescued TIPE1-caused the inhibition of cell proliferation, and administration of STAT3 inhibitor can abolish this inhibition, indicating that TIPE1 inhibits osteosarcoma proliferation primarily via PRMT1-mediated STAT3 suppression." (PMID 36151091, 2022). "Moreover, apatinib was demonstrated to enhance the sensitivity of osteosarcoma cells to doxorubicin and inhibited the doxorubicin-induced stemness phenotype through STAT3/Sox2 pathway inactivation." (PMID 36387068, 2022). "Resveratrol inhibits CSCs of osteosarcoma by the inhibition of STAT3 signaling." (PMID 35333774, 2022). "Similarly, in osteosarcoma, another signal of STAT3/Bcl-2 is also shown be involved in tumor proliferation, and the silencing of SIGLEC-15 induces the upregulation of apoptosis- and pyroptosis-related proteins." (PMID 36358792, 2022). "Moreover, increased SPP1 was found to upregulate p‐STAT3, which activated STAT3 signalling in osteosarcoma and rat hepatocytes." (PMID 35184394, 2022). "The use of active drugs confirmed the contribution of the IL-6/STAT3 axis in osteosarcoma stemness." (PMID 35582537, 2022). "Moreover, miR-331-3p affected the occurrence and development of osteosarcoma by targeting the SOCS1/JAK2/STAT3 signaling pathway." (PMID 36199788, 2022). "BD inhibited STAT3 (Signal Transducer and Activator of Transcription 3) activation that attenuated the cell proliferation, migration, invasion, and stem cell-like properties of osteosarcoma cells." (PMID 34685653, 2021). "p-STAT3 can be a predictive biomarker for lung metastasis in osteosarcoma patients." (PMID 34170850, 2021). "Furthermore, apatinib suppressed doxorubicin-induced stemness phenotype in osteosarcoma cells via STAT3 signaling." (PMID 34429133, 2021). "The other study shows FBXO2 is significantly up-regulated in osteosarcoma, which may modulate STAT3 signaling to regulate proliferation and tumorigenicity of osteosarcoma cells." (PMID 33622332, 2021). "Obviously, miR-483 inhibited the EMT of osteosarcoma by targeting STAT3." (PMID 33546665, 2021). "Therefore, STAT3 is deemed as an attractive target for chemotherapy of tumors, including osteosarcoma." (PMID 34922636, 2021). "The upregulation of STAT3 by VEGFR2 results in metastasis of osteosarcoma cells." (PMID 34769099, 2021). "In this review, we focus on recent progress on STAT3 and osteosarcoma (OS)." (PMID 33382511, 2021). "In addition, miR-106a-5p sensitizes osteosarcoma cells to cisplatin treatment by targeting signal transducer and activator of transcription 3 (STAT3)." (PMID 34365889, 2021). "Naturally, fairly poor agents on STAT3 have been developed for osteosarcoma treatment." (PMID 34922636, 2021). "It has been demonstrated STAT3 plays a vital role in osteosarcoma development and thus might be a promising target for drug discovery of human osteosarcoma." (PMID 34922636, 2021). "Interestingly, the expression of STAT3 was higher in osteosarcoma patients displaying resistant tumors and it was also associated to a poorer outcome." (PMID 34198693, 2021). "Thus, miR-483 inhibited the EMT of osteosarcoma cells by restraining STAT3 expression and inducing STAT1 expression." (PMID 33546665, 2021). "In addition, STAT3 activation was reported to promote mesenchymal stem cells-induced osteosarcoma cell survival and drug resistance while blocking STAT3 signaling revert resistance to chemotherapy in osteosarcoma Saos-2 cells to drug treatment." (PMID 34922636, 2021). "Moreover, exogenous expression of STAT3 partially blocked the miR-483-mediated suppression of the EMT in osteosarcoma cells, confirming that STAT3 functioned in the downstream of miR-483." (PMID 33546665, 2021).
osteosarcoma (continued). "Meanwhile, STAT3 facilitates the proliferation and metastasis of osteosarcoma, and the inhibition of STAT3 activity with various compounds or natural products suppresses the proliferation and migration of osteosarcoma cells or induces cell cycle arrest, apoptosis and autophagy." (PMID 33546665, 2021). "The STAT3 signaling is considered as a tumor-promoting factor in osteosarcoma." (PMID 34769099, 2021). "In summary, NHWD-870 effectively inhibit the growth of osteosarcoma by targeting STAT3 in vivo." (PMID 34168981, 2021). "Overall, the identification of NEAT1/miR-483/STAT3 axis contributed to the elucidation of the regulatory network involved in the progression of osteosarcoma and provided insights into the prognosis and development of targeted therapy for osteosarcoma in the future." (PMID 33546665, 2021). "Apatinib inhibited osteosarcoma by targeting STAT3 and reducing PD-L1/PD-L2." (PMID 34429133, 2021). "Specifically, a growing body of evidence indicated that STAT3 played a key role in the development and progression of osteosarcoma and it was commonly activated in human osteosarcoma cell lines as well as clinical osteosarcoma tissues." (PMID 34922636, 2021). "Constitutively active STAT3 has been shown to induce tumor formation in osteosarcoma." (PMID 36046775, 2020). "Knockdown of E2F1 in osteosarcoma cells results in reduced phosphorylation of STAT3." (PMID 33291686, 2020). "Thus, through the tumor cell extrinsic and intrinsic functions of PD-L2, VEGFR2 can affect both osteosarcoma cell metastasis and immune escape through the deactivation of STAT3 and the RhoA-ROCK-LIMK2 pathway." (PMID 33014879, 2020). "Interestingly, this group has also shown that STAT3 is a transcriptional activator of the expression of miR-125b, highlighting a novel feedback loop regulation between STAT3 and miR-125b in osteosarcoma." (PMID 32230926, 2020). "Additionally, VEGFR2 inhibition targeted STAT3, through which it reduced PD-L2 expression in osteosarcoma cells." (PMID 33014879, 2020). "Mechanistically, the suppressive effects of BD on osteosarcoma could be executed through inhibition of STAT3 pathway." (PMID 31631559, 2019). "Therefore, we investigated the effects of sodium cantharidate (SC), either as monotherapy and in combination with the EGFR inhibitor erlotinib, on STAT3 activation and osteosarcoma cell growth." (PMID 31422383, 2019). "The potential mechanism through which BD exhibits its anti‐osteosarcoma activity could be through the repression of STAT3 activation." (PMID 31631559, 2019). "To further confirm whether BD mediates the impeding effects on cell growth and migration by inhibiting STAT3 signaling pathway, we investigated the effects of Stattic, a potent inhibitor of STAT3 activation, on osteosarcoma cells viability and migration." (PMID 31631559, 2019). "suppressed the tumor metastasis through Stat3 signaling inhibition in osteosarcoma." (PMID 31649548, 2019). "may be a novel approach for osteosarcoma intervention because of its Stat3 signaling inhibitory activity." (PMID 31649548, 2019). "The present study tested the hypothesis that cantharidin abrogates feedback STAT3 activation induced by EGFR inhibition in osteosarcoma, resulting in enhanced tumor suppression upon combined SC and erlotinib treatment." (PMID 31422383, 2019). "Also, this study showed that NP-mediated regulation of STAT3 in osteosarcoma cells involves down regulation of protein synthesis initiation factors and inhibition of protein synthesis." (PMID 30286779, 2018). "Immunofluorescence in 143B osteosarcoma reveals that NP at 3 μM decreased the number of p-STAT3–positive cells; Western blot analysis showed that NP treatment markedly blocked STAT3 activation and phosphorylation of STAT3 in both Tyr705 and Ser727 sites in 143B and MG63 osteosarcoma cells." (PMID 30286779, 2018).
osteosarcoma (continued). "Thus, our current study shows that c-Myc, VEGF-A, and survivin are downregulated in osteosarcoma cells following the inhibition of STAT3 activity and confirms that molecular signaling downstream of STAT3 is blocked." (PMID 30286779, 2018). "STAT3 is constitutively activated in many tumors, including osteosarcoma." (PMID 30286779, 2018). "In another recent study, it was reported that icariin could reverse multidrug resistance in human osteosarcoma MG-63 doxorubicin-resistant (MG-63/DOX) cells through the blockade of STAT3 phosphorylation." (PMID 29899697, 2018). "Besides, constitutive STAT3 activation is observed in virous tumors, including some osteosarcoma tissues." (PMID 30356255, 2018). "JAK2/STAT3 blockage by resveratrol will provide a valuable strategy for osteosarcoma therapy." (PMID 30356255, 2018). "STAT3 activation is essential for the osteosarcoma-promoting effects of ADSCs." (PMID 28423603, 2017). "Additionally, mesenchymal stem cells (MSCs) in bone marrow promote osteosarcoma progression and protect tumour cells from drug-induced apoptosis through STAT3 signalling." (PMID 28423603, 2017). "Thus, the interaction between ADSCs and osteosarcoma cells is mediated, at least in part, by the STAT3 pathway." (PMID 28423603, 2017). "Furthermore, STAT3 activation was critical for osteosarcoma cell proliferation and survival in mouse xenograft osteosarcoma models." (PMID 28423603, 2017). "Furthermore, Stat3 is constitutively activated in osteosarcoma, rhabdomyosarcoma, and other soft-tissue sarcomas, and the Stat3 inactivation pathway results in apoptosis through the cleavage of caspase-319." (PMID 28054649, 2017). "Constitutive STAT3 pathway activation was recently observed in osteosarcoma." (PMID 28423603, 2017). "Thus, AMBN induced a tumor suppressive phenotype and chemosensitivity to doxorubicin via the AMBN-Src-Stat3 axis in osteosarcoma." (PMID 28054649, 2017). "The STAT3 signaling pathway is involved in Apatinib-treated osteosarcoma cells." (PMID 28837148, 2017). "Thus, ADSCs promote osteosarcoma growth and metastasis and STAT3 pathway inhibition counteracts these effects." (PMID 28423603, 2017). "Furthermore, siRNA-mediated STAT3 inhibition in osteosarcoma cells decreased cell proliferation and invasion and down-regulated MMP2/9 expression." (PMID 28423603, 2017). "Our previous research indicated that STAT3 is a critical mediator for osteosarcoma proliferation." (PMID 27340780, 2016). "Moreover, the STAT3 inhibitor cryptotanshinone can potentially be used to delay tumour progression and improve the osteosarcoma survival rate." (PMID 26623559, 2016). "Finally, we demonstrated that increased expression of p-STAT3, multidrug resistance protein (MRP) and P-glycoprotein (MDR-1) was associated with high chemotherapy resistance in clinical osteosarcoma samples." (PMID 27340780, 2016). "It is especially notable that osteosarcoma cells that express relatively high levels of STAT3, either activated by drugs or induced by MSCs in its environment, were significantly sensitized to the apoptotic effects of drugs by STAT3 inhibition." (PMID 27340780, 2016). "Here, we showed that MSCs activate STAT3 signaling in osteosarcoma cells both in vitro and in vivo." (PMID 27340780, 2016). "This study investigated whether 4-MD can mediate its anti-proliferative and apoptotic effects in human osteosarcoma cells through the suppression of the JAK2/STAT3 pathway." (PMID 26755649, 2016). "To determine whether STAT3 signaling is involved in MSC-induced osteosarcoma survival, we assessed whether activated STAT3 levels were increased in response to MSC-CM treatment." (PMID 27340780, 2016). "In addition, we detected the expression of vascular endothelial growth factor (VEGF) and signal transducer and activator of transcription 3 (STAT3) in osteosarcoma cell treated with Eag1 small interfering RNAs (siRNAs)." (PMID 26783521, 2015).
osteosarcoma (continued). "Furthermore, treatment with CDDO-Me inhibited the Stat3 pathway with decreased levels of Bcl-xL, survivin and Mcl-1 proteins in multi-drug resistant osteosarcoma cell lines." (PMID 26244918, 2015). "Specifically, in U2OS osteosarcoma cells, a high level of cytoplasmic Stat3 inhibits PKR." (PMID 26406898, 2015). "Moreover, a similar pattern was observed in osteosarcoma cell proliferation and migration suppression between STAT3 siRNA and Eag1 siRNAs groups." (PMID 26783521, 2015). "In addition, inhibition of STAT3 plays a role in proliferation, apoptosis and migration in osteosarcoma cells in vitro." (PMID 25146150, 2014). "Furthermore, activation of STAT3 in several cancers has been found to be correlated with clinical outcome especially in osteosarcoma." (PMID 25146150, 2014). "STAT3 has been shown to be dysregulated in nearly every major cancer, including osteosarcoma (OS)." (PMID 23244668, 2012). "Stat3 pathway was activated in osteosarcoma tissues and in MDR cell lines." (PMID 20459702, 2010). "Activation of Stat3 pathway was also reported to be present in osteosarcoma cells and tissues." (PMID 20459702, 2010). "In addition, LLL3, Stat3 DNA binding and transcription activities inhibitor, and Stat3 siRNA significantly decrease cell proliferation and viability, ultimately inducing apoptosis in osteosarcoma cells." (PMID 20459702, 2010). "Our data strongly support that the activated Stat3 pathway could serve as a therapeutic target in rhabdomyosarcoma and osteosarcoma cancers using a dominant negative Stat3 mutant or a small molecule Stat3 inhibitor, STA-21." (PMID 17598902, 2007). "Thereafter, we hypothesized that inhibition of Stat3 should lead to suppression of osteosarcoma and rhabdomyosarcoma cell growth." (PMID 17598902, 2007). "Taken together, Stat3 may serve as a therapeutic target in human osteosarcomas and rhabdomyosarcomas." (PMID 17598902, 2007). "Therefore, we speculated that DUSP3 affects the stemness of osteosarcoma cells by regulating the EGFR/STAT3/SOX2 axis." (PMID 39744427, 2025). "Thus, our results indicated that DUSP3 regulates the STAT3/SOX2 axis in osteosarcoma." (PMID 39744427, 2025). "Therefore, one can speculate that the STAT3 pathway might facilitate the spread of CTCs for the formation of an immunosuppressive osteosarcoma microenvironment." (PMID 36849442, 2023). "A previous study showed that TSN could inhibit osteosarcoma growth by targeting STAT3." (PMID 37946196, 2023). "Furthermore, in 80 osteosarcoma patients, the mean expressions of p-JAK2 and STAT3 in primary osteosarcoma tissues with lung metastasis (9.23 and 14.82, respectively) are much higher than those without lung metastasis (2.43 and 5.06, respectively), and a positive correlation is evident between both." (PMID 36923933, 2023). "Gene expression and Ingenuity Pathway Analysis (IPA) analyses demonstrated that the STAT3 pathway was inhibited after transfection of a TIPE1 expression vector, suggesting that TIPE1 could inactivate the STAT3 signaling pathway and inhibit the malignant biological behavior of osteosarcoma." (PMID 36151091, 2022). "However, how STAT3 and its partners precisely regulate the occurrence and progression of osteosarcoma remains unclear." (PMID 36151091, 2022). "In our study, diosmetin inhibited tumor cell proliferation and promoted apoptosis as well as suppressed STAT3/c-Myc signaling pathway in osteosarcoma cells, which is consistent with the inhibitory effects of another STAT3 inhibitor toosendanin on cell proliferation of osteosarcoma 143B Cells." (PMID 34922636, 2021). "In addition, apatinib has been shown to inhibit osteosarcoma cell proliferation and induce osteosarcoma cell apoptosis and G0/G1 phase arrest in vitro, and inhibit cell invasion, migration and PD-1 expression, and the STAT3/ Bcl-2 signaling pathway is considered as a possible mechanism." (PMID 33892656, 2021).